DPP4 (dipeptidyl peptidase 4)
Diseases named in the same sentence as DPP4 in open-access papers (continued):
Sharing a sentence is not in itself a finding about the gene and the disease.
type 2 diabetes (continued). "In conclusion, sotagliflozin seems to represent a promising treatment for both type 1 and type 2 diabetes, either alone or in combination with metformin or DPP-4 inhibitors in type 2 diabetes or, with an adequate insulin protocol, in type 1 diabetes." (PMID 30819210, 2019). "Between 2006 and 2013, the DPP-4 inhibitors were approved for glucose-lowering use in type 2 diabetes both by the FDA and by the European Medicines Agency (EMA)." (PMID 31275243, 2019). "Dipeptidyl peptidase-4 (DPP-4) inhibition is an established glucose-lowering therapy in type 2 diabetes." (PMID 31275243, 2019). "DPP-4 inhibitors were thereby considered mainly as early therapy in combination with metformin in subjects with type 2 diabetes." (PMID 31275243, 2019). "The dipeptidyl peptidase-4 inhibitor saxagliptin is a widely used antihyperglycemic agent in patients with type 2 diabetes." (PMID 31308448, 2019). "The development of the DPP-4 inhibition concept for glucose-lowering therapy in type 2 diabetes originated on the fundament of the incretin concept." (PMID 31275243, 2019). "A pooled analysis of four studies showed that DPP-4 inhibitors led to a significant reduction in albuminuria in patients with type 2 diabetes." (PMID 30616638, 2019). "This article gives an overview on the characteristics of the various DPP-4 inhibitors in clinical use and highlights the positioning of the drug class in the guidelines for the treatment of type 2 diabetes." (PMID 31275246, 2019). "In later stages of type 2 diabetes, DPP-4 inhibitors are also recommended in the guidelines in triple therapies with metformin and SGLT-2 inhibitors or with metformin and insulin." (PMID 31275246, 2019). "Dipeptidyl dipeptidase-4 (DPP-4) inhibitors (DPP-4 i) have been broadly applied in clinical aspects for controlling blood glucose levels in type 2 diabetic patients (T2DP)." (PMID 30889182, 2019). "Recently, dipeptidylpeptidase 4 (DPP-4) inhibitors have gained attention for the treatment of type 2 diabetes." (PMID 30834241, 2019). "GLP-1 agonists and dipeptidyl peptidase-4 (DPP-4) inhibitors (that prevent the degradation of the GLP-1) have been approved for the treatment of type 2 diabetes." (PMID 31231210, 2019). "DPP-4 inhibitors have been increasingly used for hyperglycemic control in type 2 diabetes with good tolerance although its benefit in type 1 diabetes is controversial." (PMID 30591063, 2018). "Dipeptidyl peptidase-4 (DPP-4) inhibitors are rapidly becoming a first-line treatment option for patients with type 2 diabetes in Japan." (PMID 29435909, 2018). "Alogliptin benzoate, a member of dipeptidyl peptidase-4 inhibitors, is a recent drug developed by Takeda Pharmaceutical Company for the treatment of Type 2 diabetes; it potentiates the effect of incretin hormones through the inhibition of their degradation." (PMID 30345140, 2018). "Recently, several new classes of drugs have been developed for treating type 2 diabetes, which include dipeptidyl peptidase-4 (DPP4) inhibitors, glucagon-like peptide-1 (GLP-1) receptor agonists and SGLT2 antagonists." (PMID 29867503, 2018). "We enrolled 14 patients with type 2 diabetes and hypertriglyceridemia treated with statins and dipeptidyl peptidase-4 inhibitors with glycated hemoglobin (HbA1c) < 8.0%, LDL-C < 120 mg/dL, and fasting triglyceride ≥150 mg/dL." (PMID 29544483, 2018). "Saxagliptin is an orally active, once-daily, selective and reversible inhibitor of DPP-4 enzyme indicated/approved as an adjunct to diet and exercise to improve glycemic control in adults with type 2 diabetes." (PMID 29787616, 2018). "GLP-1 receptor agonists, DPP-4 inhibitors, and metformin have beneficial effects on cardiovascular complications in patients with type 2 diabetes, as well as in patients with reperfusion after ischemia." (PMID 29670459, 2018).
type 2 diabetes (continued). "Asian patients with type 2 diabetes are generally characterized by defective early phase insulin secretion, DPP-4 inhibitors can improve impaired insulin secretion and then exert greater effects in HbA1c in patients with type 2 diabetes." (PMID 29780322, 2018). "Dipeptidyl peptidase-4 (DPP-4) inhibitors are also one of the newer types of oral glucose-lowering drug licensed for type 2 diabetes, with the first-in-class sitagliptin having been approved in 2006 in the United States." (PMID 29491123, 2018). "As have other DPP-4 inhibitors, linagliptin has demonstrated glucose-lowering efficacy and tolerability in type 2 diabetes patients with kidney disease." (PMID 29491123, 2018). "Dipeptidyl peptidase-4 (DPP-4) inhibitors (gliptins) are approved drugs for the treatment of hyperglycemia in patients with type 2 diabetes." (PMID 29776406, 2018). "Dipeptidyl peptidase-4 inhibitors (DPP4is) are drugs that are commonly used as second-line agents for the treatment of type 2 diabetes (T2D)." (PMID 29549573, 2018). "In conclusion, patients initiating DPP-4 inhibitors as third-line therapy in type 2 diabetes appeared to have lower discontinuation and have less hypoglycemia when compared to patients starting NPH insulin." (PMID 29713649, 2018). "This multinational cohort study examines the association of second-line treatment (sulfonylureas, dipeptidyl peptidase 4 inhibitors [DPP-4], or thiazolidinediones) for type 2 diabetes after initial therapy with metformin with hemoglobin A1c (HbA1c) levels." (PMID 30646124, 2018). "Dipeptidyl peptidase 4 (DPP-4) inhibitors (gliptins) are a relatively new class of oral antidiabetic drugs for the treatment of type 2 diabetes." (PMID 29787616, 2018). "This function is defective in type 2 diabetes, presumably because DPP-4 activity is enhanced in patients with glucose intolerance." (PMID 29310647, 2018). "DPP4 inhibitors (gliptins) are commonly used antidiabetic drugs for the treatment of type 2 diabetes." (PMID 29531541, 2018). "DPP-4 inhibitors represent an attractive therapeutic option for the control of hyperglycemia in patients with type 2 diabetes due to their ease of use, tolerability and safety profile." (PMID 29310647, 2018). "The SGLT2 inhibitor was associated with a significant increase in HDL-C and LDL-C after 24 weeks of SGLT2 inhibitor treatment in patients with type 2 diabetes compared with those with DPP-4 inhibitor treatment in this study." (PMID 28403877, 2017). "Studies of dipeptidyl peptidase (DPP)-4 inhibitors report heterogeneous effects on endothelial function in patients with type 2 diabetes (T2D)." (PMID 28109295, 2017). "DPP-4 inhibitors appear to be safer compared to other anti-diabetic medications to treat older people with type 2 diabetes." (PMID 29047372, 2017). "Dipeptidyl peptidase-4 (DPP-4) inhibitors are widely used blood glucose-lowering drug for treatment of type 2 diabetes." (PMID 29195509, 2017). "The results of this SR show that further research is needed on the clinically relevant short and long-term risks and benefits of the use of DPP-4 inhibitors for the management of type 2 diabetes in older adults." (PMID 29047372, 2017). "Multivariate regression analysis after adjustment with age and gender demonstrated that average triglyceride and basal HbA1c were independent factors determining the durability of DPP-4 inhibitor in subjects with type 2 diabetes." (PMID 28626771, 2017). "DPP-4 inhibitors have been recommended as second line drugs for the management of type 2 diabetes in older adults by several expert groups because of their lower risk of hypoglycaemia." (PMID 29047372, 2017). "Especially, DPP-4 inhibitor is widely used in Japan, because the pathophysiology of type 2 diabetes in Japanese is primarily characterized by β-cell dysfunction and less insulin resistance compared with that in Caucasians." (PMID 28626771, 2017).
type 2 diabetes (continued). "Even after adjustment with age and gender, average triglyceride and basal HbA1c were independent factors contributing to the efficacy of DPP-4 inhibitor in subjects with type 2 diabetes." (PMID 28626771, 2017). "From the results of our SR and the additional references of interest we developed one recommendation in relation to DPP-4 inhibitors use in older people with type 2 diabetes." (PMID 29047372, 2017). "Dipeptidyl peptidase-4 (DPP-4) inhibitors are often used all over the world and exert various beneficial effects including glucose-lowering effect in many subjects with type 2 diabetes." (PMID 28626771, 2017). "Over the last decade, glucagon-like peptide-1 (GLP-1) analogues and inhibitors of the GLP-1-degrading enzyme dipeptidyl peptidase-4 (DPP-4) have been implemented as treatments for type 2 diabetes." (PMID 28551699, 2017). "From January 2013 to December 2015, a total of 228 patients with type 2 diabetes who were receiving a DPP-4 inhibitor or SGLT2 inhibitor as add-on therapy to metformin and/or a sulfonylurea were consecutively enrolled." (PMID 28403877, 2017). "DPP-4 inhibitors have been found to increase active GLP-1 concentrations by 2-3-fold in type 2 diabetes." (PMID 29100378, 2017). "To elucidate the independent factors determining the efficacy of DPP-4 inhibitor in all participants with type 2 diabetes, we performed a multivariate regression analysis." (PMID 28626771, 2017). "In this study, we therefore asked whether common genetic variation [minor allele frequency (MAF) ≥0.05] in the DPP4 gene exists that affects incretin levels, insulin secretion, and glucose tolerance in non-diabetic individuals recruited from the TÜbingen Family study for type 2 diabetes (TÜF)." (PMID 28750074, 2017). "Third, the previous reports showed that DPP-4 inhibitor is effective in patients with type 2 diabetes with high serum eicosapentaenoic acid concentrations." (PMID 28626771, 2017). "To elucidate the factors related with the efficacy of DPP-4 inhibitors in subjects with type 2 diabetes, we analyzed the difference of clinical background between the effective group and ineffective group." (PMID 28626771, 2017). "To elucidate the independent factors determining the efficacy of DPP-4 inhibitor in the obese group with type 2 diabetes, we performed a multivariate regression analysis." (PMID 28626771, 2017). "DPP4 is a well-characterized therapeutic target for type II diabetes treatment, and there have been extensive drug discovery activities reported in this area." (PMID 28507818, 2017). "GLP-1 mimetic drugs or DPP4 inhibitors that increase plasma GLP-1 level have already shown huge potential to treat type 2 diabetes." (PMID 28793909, 2017). "Based on the guideline and potential, the incretin-based drug especially DPP-4 inhibitor is considered as a first choice therapy in Japanese type 2 diabetes patients." (PMID 29057274, 2017). "Even after adjustment with age and gender, average triglyceride level was an independent factor contributing to the efficacy of DPP-4 inhibitor in the obese group with type 2 diabetes." (PMID 28626771, 2017). "Chinese scholars conducted a systematic review and meta-analysis to evaluate the effects of dipeptidyl peptidase-4 inhibitors on blood pressure in patients with type 2 diabetes, and fifteen trials involving 5636 participants were identified." (PMID 29340105, 2017). "DPP-4 inhibitors, including vildagliptin and sitagliptin, are oral anti-hyperglycemic agents for the treatment of type 2 diabetes." (PMID 27759084, 2016). "An orally administered dipeptidyl peptidase 4 (DPP-4) inhibitor is now available for treatment of type 2 diabetes." (PMID 27624168, 2016). "The relationship between treatment with a DPP-4 inhibitor and endothelial function in patients with type 2 diabetes has been evaluated." (PMID 27624168, 2016). "GLP-1 analogues and DPP-4 inhibitors belong to one of the incretin-based therapies for type-2 diabetes." (PMID 27304951, 2016).
type 2 diabetes (continued). "The aim of the present study was to investigate the organ-specific protective effects of DPP-4 inhibitor in rodent model of type 2 diabetes." (PMID 26959365, 2016). "Dipeptidyl peptidase-4 inhibitor, exemplified by sitagliptin, is highly efficacious in treating type 2 diabetes (T2DM), yet little is known if sitagliptin exerts beneficial effects on microbiota associated with obesity and T2DM." (PMID 27631013, 2016). "We showed that the DPP-4 inhibitor exhibited dose-dependent organ-specific effects on the cardiovascular complications of a type 2 diabetes model." (PMID 26959365, 2016). "This meta-analysis included a comprehensive search for all trials with incretin-based therapies (GLP-1 receptor agonists and DPP-4 inhibitors) for type 2 diabetes treatment." (PMID 27078018, 2016). "They investigated the effect of the combination of DPP-4 inhibitors with ARB in type 2 diabetic patients with incipient nephropathy." (PMID 27483245, 2016). "Altered DPP4 activity has been reported in a number of diseases, including type 2 diabetes and tumor biology." (PMID 26881257, 2016). "Trelagliptin (SYR-472, zafatek) is a novel once-weekly DPP4 inhibitor that shows sustained efficacy by once-weekly dosing regimen in patients with type 2 diabetes." (PMID 27328054, 2016). "Clinical trials in patients with type 2 diabetes demonstrated that DPP-4 inhibitors improve endothelial function, as measured by reactive hyperaemia peripheral arterial tonometry and flow-mediated dilatation." (PMID 27184495, 2016). "Trelagliptin (SYR-472), a novel dipeptidyl peptidase-4 inhibitor, shows sustained efficacy by once-weekly dosing in type 2 diabetes patients." (PMID 27328054, 2016). "Further studies enrolling a large number of subjects are needed to confirm the long-term effect of a DPP-4 inhibitor on endothelial function in patients with type 2 diabetes." (PMID 27624168, 2016). "The present study helps generate new information for further structural optimization and can influence the development of new DPP-4 inhibitors discoveries in the treatment of type-2 diabetes." (PMID 27304951, 2016). "As a sub-analysis of the PROLOGUE study, we evaluated the long-term effect of sitagliptin, a dipeptidyl peptidase 4 inhibitor, on endothelial function in the conduit brachial artery in patients with type 2 diabetes." (PMID 27624168, 2016). "As DPP4 inhibitors are a class of widely used therapeutics for the management of type II diabetes, they are considered to be safe and well tolerated." (PMID 27137491, 2016). "Subsequently, a new class of oral hypoglycemic agents for the treatment of type 2 diabetes were emerged and these are called DPP-4 inhibitors, which restrain the action of DPP-4 thereby prolonging incretin effect in vivo." (PMID 27832184, 2016). "Linagliptin, a xanthine derivative, is a highly potent, selective, long-acting and orally bioavailable DPP-4 inhibitor for the treatment of type 2 diabetes." (PMID 27517889, 2016). "Use of dipeptidyl peptidase-4 (DPP-4) inhibitors is a strategy for glucose-lowering treatment in type 2 diabetic patients." (PMID 27652270, 2016). "Linagliptin is a dipeptidyl peptidase-4 (DPP-4) inhibitor that was approved for the treatment of type 2 diabetes in 2011." (PMID 26981294, 2016). "DPP4 was considered as a therapeutic target for type 2 diabetes as it degrades incretins: glucagon-like peptide- (GLP-) 1 and gastric inhibitory peptide (GIP)." (PMID 26881257, 2016). "DPP4 is thought to play a role in glucose homeostasis and type-2 diabetes by inactivating incretin hormones involved in glucose-dependent insulin secretion." (PMID 25651499, 2015). "In clinical trials, the DPP-4 inhibitor sitagliptin was also shown to decrease LDL-C levels in Japanese patients with type 2 diabetes, suggesting that this lipid-lowering effect is characteristic of this class of compound." (PMID 25995772, 2015).
type 2 diabetes (continued). "Dipeptidylpeptidase 4 (DPP-4) inhibitors are a new class of blood glucose-lowering drug and used for treatment of type 2 diabetes." (PMID 25986579, 2015). "Clinical studies have revealed that the long-term administration of DPP4 inhibitors improves the postprandial atherogenic levels of TG-rich lipoprotein and/or endothelial dysfunction in patients with type 2 diabetes and healthy volunteers." (PMID 25452780, 2015). "Combined DPP4 inhibitor and insulin therapy was introduced in Japan in 2013, and numerous patients with type 2 diabetes receiving insulin began to additionally receive DPP4 inhibitors." (PMID 25780477, 2015). "Another study reported that high serum levels of soluble DPP-4 correlated with poor response to sitagliptin in Japanese patients with type 2 diabetes." (PMID 25699116, 2015). "The combination of dipeptidyl peptidase-4 (DPP-4) inhibition with insulin is a glucose lowering strategy for the treatment of type 2 diabetes which has gained considerable interest during recent years." (PMID 26587020, 2015). "The effect of DPP4 inhibition on scratch repair has been analyzed also in N-HEK as well as in human adult epidermal keratinocytes obtained from patients with type II diabetes (D-HEK)." (PMID 26136686, 2015). "DPP-4-inhibitor monotherapy has been shown to decrease the GA level by 2.9 % in drug-naïve Japanese patients with type 2 diabetes undergoing HD." (PMID 25995772, 2015). "Accumulating lines of evidence suggest the beneficial effects of DPP-4 inhibitors include not only type 2 diabetes but also various types of cardiovascular diseases." (PMID 25768281, 2015). "The renal effects of DPP4 inhibition have been previously explored in animal models of Type 1 and Type 2 diabetes." (PMID 26509887, 2015). "Sitagliptin is one of the dipeptidyl peptidase-4 (DPP-4) inhibitors and is widely used in the treatment of type 2 diabetes." (PMID 25883713, 2015). "DPP-4 inhibitors have salutary effects not only on type 2 diabetes but also on certain cardiovascular diseases." (PMID 25768281, 2015). "There are few studies evaluating long-term glycemic control using a dipeptidyl peptidase-4 inhibitor in type 2 diabetes patients with end-stage renal disease (ESRD)." (PMID 26550558, 2015). "Dipeptidyl peptidase-4 (DPP-4) inhibitors are a class of agents that were recently approved for the treatment of type 2 diabetes." (PMID 25992614, 2015). "It is estimated that DPP4 inhibitors have been used in as many as 3 million patients with type 2 diabetes since sitagliptin was first launched on the Japanese market in 2010." (PMID 25780477, 2015). "Most of the findings about inhibition of DPP4 are related to type II diabetes in human patients, opening up new perspectives in therapy." (PMID 26291537, 2015). "DPP-4 inhibitors also preserves islet function in both type 1 and type 2 diabetes animal models and increases pancreatic insulin content, through an increase in proliferation, neogenesis, and apoptosis resistance of beta cells." (PMID 26609328, 2015). "Although the DPP-4 inhibitor is a drug for the treatment of Type 2 diabetes, it has been reported to play a protective role in cardiovascular disease via both GLP-1 dependent and independent effects." (PMID 25876091, 2015). "In Japan, dipeptidyl peptidase 4 (DPP4) inhibitors have become standard therapeutic agents for type 2 diabetes, and numbers of patients receiving insulin therapy combined with DPP4 inhibitors, which is a highly effective regimen, are increasing." (PMID 25780477, 2015). "Because GLP-1 analogues and DPP-4 inhibitors appear to offer many advantages for treating type 2 diabetes, they have gained a rapid growth in use in the past decade." (PMID 26290759, 2015). "Inhibition of the DPP-4 system trends a new approach in the management of Type-2 diabetes by virtue of its effects on extending the half-life of glucose-dependent insulinotropic peptide (GLP-1) and glucagon-like peptide-1 (GIP)." (PMID 25876091, 2015).